VHL (von Hippel-Lindau tumor suppressor)
Diseases named in the same sentence as VHL in open-access papers (continued):
Sharing a sentence is not in itself a finding about the gene and the disease.
autosomal dominant disease (8 papers, 2012 to 2026). Autosomal dominant form of disease. "Von Hippel-Lindau syndrome (VHL) is an autosomal dominant disease caused by a genetic aberration of the tumor suppressor gene VHL and characterized by multi-organ tumors." (PMID 34963877, 2022). "It represents an autosomal dominant inherited disorder caused by germline mutations in the VHL gene." (PMID 27819754, 2017). "The autosomal dominant disease is caused by mutations in the VHL gene." (PMID 22799452, 2012).
genetic disease (8 papers, 2010 to 2026). "VHL is a genetic disease and detection of heterozygous VHL mutations via MLPA reinforces the diagnostic link between clinical, pathological, and molecular findings in this family cohort." (PMID 41302074, 2025). "Von Hippel-Lindau (VHL) is a rare genetic disorder caused by mutations in the VHL gene on chromosome 3." (PMID 41302074, 2025). "While the cases presented here follow the general lines for VHL disease, patients are related to each other, present tumors of the nervous system and mutations in the VHL gene, their particularities of presentation and manifestation bring new insights into this rare genetic disease." (PMID 41302074, 2025). "For the other hypothesis, MSNN would derive from two different cell types, arising from a predisposing genetic disorder, such as VHL." (PMID 40918781, 2025). "The frequency of PNETs with hereditary disease is high in the order of MEN1, VHL, NF-1 and TSC." (PMID 22824559, 2012).
benign tumors (7 papers, 2015 to 2025). "HIF-2α has been considered the ideal target, as it is upregulated with loss of the VHL gene and is thought to be the main oncogenic driver of both malignant and benign tumors." (PMID 36310638, 2022). "To analyze whether VHL is associated with hepatic I/R injury, we first assessed VHL expression in the livers of patients who underwent benign tumor partial hepatectomy." (PMID 39585306, 2024). "In the present study, we confirmed that VHL upregulation was closely related to hepatic I/R injury in samples from patients with liver resection for benign tumors and in mouse models." (PMID 39585306, 2024). "The absence of VHL in cardiomyocytes leads to degeneration, malignant transformation, and failure of the heart, confirming the essential role of the cullin-2-elonginB/C-VHL complex for the regulation of Hif1-α and its effects on cardiac physiology and development." (PMID 33114658, 2020).
CNS tumors (7 papers, 2016 to 2025). "This discrepancy could be linked to poorer preoperative functional status in VHL patients due to the cumulative burden of CNS tumors or multiple spinal tumors." (PMID 39950840, 2025). "The increase in total CNS tumor volume over time in VHL patients seems to progress in a saltatory manner, much as individual tumors." (PMID 36441756, 2022). "Specifically, the thousands of patients with VHL studied at the NIH in a natural history protocol for CNS tumors has allowed for an understanding of the potential catastrophe of these tumors, particularly in their infrequent occurrence in surgically unrespectable locations." (PMID 28094316, 2017). "This case highlights the importance of considering TTM among the differential diagnoses for CNS tumors, even in the absence of VHL." (PMID 40726878, 2025).
kidney disease (7 papers, 2013 to 2023). "Besides, mouse models combined with VHL deletion and the target molecular loss are highly favoured when studying the mechanisms underlying various kidney diseases." (PMID 37933774, 2023). "It is worth noting that Von Hippel–Lindau (VHL) is an important regulatory molecule in the pathogenesis of kidney diseases." (PMID 37933774, 2023). "Mutations in E3 ligases complex (e.g., KLH3 and CUL3 or VHL) lead to altered protein degradation by the UPS and subsequently to kidney disease." (PMID 33171965, 2020).
hematological disorder (6 papers, 2015 to 2025). "CRBN-based degraders frequently excel in hematologic malignancies, while VHL-based PROTACs show advantages in certain solid tumors." (PMID 41369129, 2025). "An improved understanding of the molecular mechanisms underpinning the VHL gene’s role in hematological disorders is increasingly becoming crucial." (PMID 39376720, 2024).
adenocarcinoma (4 papers, 2017 to 2023). A common cancer characterized by the presence of malignant glandular cells.
mitochondrial disease (4 papers, 2016 to 2023). "FG-4592 mimics the VHL KO by inducing hypoxia response and was shown to rescue the growth defect caused by moderate and severe mitochondrial disease conditions in human cell lines." (PMID 34680998, 2021).
neurodegenerative disease (2 papers, 2016 to 2025). A disorder of the central nervous system characterized by gradual and progressive loss of neural tissue and neurologic function. "In the context of neurodegenerative diseases, VHL interacts with DJ-1 and prevents HIF1α degradation by CUL2, which may partly explain the neuroprotective role of DJ-1 in Parkinson’s disease." (PMID 26751167, 2016).
bacterial infections (1 paper, 2021). "The cytokine pattern as well as the relative abundance of M1 macrophages in lesions from VHL KO mice may contribute to reduced angiogenesis and improved control of bacterial infections." (PMID 34349124, 2021).
haematopoietic cancer (1 paper, 2012). "Strong synergy is seen in neuronal, renal, breast, lung, and haematopoietic cancer cells harboring abnormalities in PTEN, VHL, LKB1, Her2, or KRAS." (PMID 23155392, 2012).
neoplastic disorder (1 paper, 2025). "Von Hippel-Lindau syndrome (VHL) is a rare hereditary neoplastic disorder caused by mutations in the VHL gene." (PMID 40796357, 2025).
VHL also shares sentences with these, for which no sentence is quoted: renal tumors (8 papers); Spinal hemangioblastoma (7); head and neck paraganglioma (6); endocrine glands tumors (3); heart failure (3); hereditary cancer (3); papillary carcinoma (3); retinoblastoma (3); sarcoma (3); small cell lung carcinoma (3); Birt-Hogg-Dube syndrome (2); cardiovascular disease (2); dilated cardiomyopathy (2); endocrine tumors (2); hereditary renal cell carcinoma (2); hereditary retinoblastoma (2); hyperparathyroidism (2); Li-Fraumeni syndrome (2); lung fibrosis (2); pancreas (2); skin cancer (2); thyroid (2); Wilms tumor (2); -deficient (1); 3p- syndrome (1); achondroplasia (1); acute promyelocytic leukemia (1); adrenocortical adenoma (1); Airway obstruction (1); anaplastic thyroid cancer (1).
A further 111 diseases each share a sentence with VHL in 1 paper.